ACE (angiotensin I converting enzyme)
Diseases named in the same sentence as ACE in open-access papers (continued):
Sharing a sentence is not in itself a finding about the gene and the disease.
diabetes (continued). "3P-MACE HRs were significantly in favor of GLP-1RA irrespectively of sex, in those aged 65 years or older, with longer diabetes duration, not treated with long-acting insulin, not treated with sulfonylureas, treated with ACE inhibitors, but irrespectively of statin treatment." (PMID 32522260, 2020). "This decrease needs to be discussed with respect to the warning published by the European Medicines Agency in 2012 that the combination of aliskiren with ACE inhibitors and ARBs is no longer recommended for patients and is contraindicated in patients with diabetes or kidney problems." (PMID 30848243, 2019). "The overall incidence of AKI was 17.7% (n = 44) and the AKI group had a significantly higher rate of medical comorbidities, including diabetes (P < 0.001), pre-existing renal disease (P < 0.001), and medication with an ACE inhibitor (P = 0.037) than the non-AKI group." (PMID 30917804, 2019). "In the diabetes group, 67% were on a beta blocker (compared to pre-diabetes 63% and no diabetes 55%, p = 0.01), 61% were on an ACE inhibitor or ARB (compared to pre-diabetes 54% and no diabetes 52%, p = 0.03) and 70% were on a statin (pre-diabetes 52% and no diabetes 44%, p < 0.001)." (PMID 30202020, 2018). "Indeed the renoprotective effects of ACE inhibition, now routinely used in diabetes management, were initially examined in a non-diabetic experimental model of raised intraglomerular pressure: the subtotally nephrectomized (SNx) rat19." (PMID 28611444, 2017). "Other studies proved that combination therapy with one RAS inhibitor (ACE inhibitor or ARB) and one vitamin D analog (paricalcitol or doxercalciferol) leads to additive or synergistic therapeutic effects in blocking renal injury in experimental rat models of type 1 and type 2 diabetes mellitus." (PMID 23843788, 2013). "At the time of reporting severe hypoglycemic events, participants and staff were also asked about changes in medications that were not used to treat diabetes but known to either lower blood glucose or mask the symptoms of low blood glucose (e.g. beta blockers or ACE inhibitors)." (PMID 22646230, 2012). "However, since AT2R inhibits ACE activity, we speculated that AT2R in diabetes might lead to heightened ACE2 activity and then to an increased ACE2/ACE ratio, which could be important in vasodilatation and natriuresis in DN." (PMID 22110472, 2011). "Taken together, these data suggest that intratubular Ang II is increased in proximal tubules of AT2RKO with or without diabetes; the increased ACE/ACE2 ratio might accelerate, at least in part, favoring the development of DN." (PMID 22110472, 2011). "ACE inhibitors may also increase survival in diabetes patients without heart disease and some large studies have shown that ACE inhibitors were able to reduce the risk of developing diabetes itself." (PMID 19061507, 2008). "Thus, ACE and AGTR1 could be involved in diabetes and dyslipidaemia." (PMID 39080710, 2024). "Interestingly, angiotensin converting enzyme (ACE) inhibitors-treated diabetic patients had lower vitreous levels of VEGF, indicating that angiotensin II may also contribute to the elevated levels of VEGF seen in diabetes mellitus." (PMID 32426041, 2020). "In the US, a diabetes care improvement in public health clinics found lower incidence of complications but the cost of individual improvements in care varied and all interventions but the use of an Angiotensin-converting enzyme (ACE) inhibitor, were not cost-effective." (PMID 32122378, 2020). "In a stepwise regression analysis only use of ACE inhibitors remained inversely correlated with SOD activity (r2 = 0.13, p<0.0001) and no independent association or correlation was observed with age, duration of diabetes, HbA1c levels or diabetic retinopathy status (data not shown)." (PMID 24819633, 2014).
diabetes (continued). "Moreover, the widespread use of ACE-inhibitors and angiotensin receptor blockers in the diabetic subjects may have counterbalanced a presumed negative effect of diabetes on Klotho production." (PMID 23945089, 2013). "Three studies reported on the relationship between perioperative useof ACE inhibitors and SHG in patients without diabetes after cardiac surgery." (PMID 39867189, 2025). "Evidence from landmark clinical trials consistently demonstrates the kidney-protective effects of ACE inhibitors and ARBs in patients with CKD and albuminuria, both with and without diabetes." (PMID 41234923, 2025). "Only one person in the diabetes group received antihypertensive treatment, and none received ACE inhibitor treatment; 16 people in the DKD group received ACE inhibitors or antihypertensive therapy." (PMID 37525631, 2023). "Furthermore, a few studies suggested an association between ACE genotype and tendency to higher BP in normoalbuminuric, normotensive patients during ABPM measurements in T1DM children, but to date, there are no studies exploring this in adolescents and young adults with HT and diabetes." (PMID 24562335, 2014). "Moreover, although diabetes mellitus was identified as a predictor of HDL-C, ApoA, LDL-C and glucose, neither ACE I/D nor AGTR1 rs5182 contributed to changes in lipid and lipid ratios in males." (PMID 39080710, 2024). "Secondary preventive ACE inhibitors/angiotensin receptor blockers (ARBs) and P2Y12-inhibitors were more frequently used in patients with type 1 diabetes compared to propensity score-matched patients without diabetes." (PMID 36068573, 2022). "Indeed, several, small-scale studies with relatively short follow-up found that dual RAS blockade combining an ACE inhibitor and an ARB may reduce albuminuria more effectively than single blockade with ACE inhibitor or ARB monotherapy in subjects with or without diabetes." (PMID 34260595, 2021).
heart failure (1,197 papers, 2005 to 2026). Inability of the heart to pump blood at an adequate rate to meet tissue metabolic requirements. "Asystole has also been associated with the use of other drugs such as amiodarone, the anesthetic propofol and various angiotensin-converting enzyme (ACE) drugs used to lower blood and reduce the risk of heart failure." (PMID 40699698, 2025). "ACE inhibitors are known to help treat cardiovascular and kidney diseases, with the ability to cause vasodilation, reduce blood pressure, and help treat heart failure, diabetes mellitus, diabetic nephropathy and stimulate natriuresis." (PMID 40649895, 2025). "Our base case analysis reveals that ACE inhibitors, the stalwarts of heart failure management, are associated with a lower mean cost of $15,000 compared to ARBs." (PMID 39252272, 2024). "In another study with perindopril, PREAMI, patients over 65 years of age with myocardial infarction and normal ejection fraction were evaluated, and administration of this ACE led to a significant decrease in the risk of heart failure and death." (PMID 39062156, 2024). "Despite pharmacological advancements such as β-blockers and angiotensin-converting enzyme (ACE) inhibitors, which have effectively reduced mortality rates, the residual risk of developing heart failure post-MI remains considerable." (PMID 39660125, 2024). "Our analysis also identified intolerance to beta-blockers of angiotensin-converting enzyme (ACE) inhibitors as a marker of advanced heart failure, which has known associations with advanced heart failure in the published literature." (PMID 38355512, 2024). "If there are signs of heart failure, an aldosterone inhibitor associated with angiotensin-converting enzyme (ACE) inhibitors is recommended (expert opinion: 30.8% strongly agree; 38.5% agree)." (PMID 36918011, 2023). "The RALES (Randomized Aldactone Evaluation Study) showed that SP added to ACE inhibitor therapy reduces the risk of sudden cardiac death (SCD) in patients with severe heart failure and a reduced left-ventricular ejection fraction." (PMID 36836569, 2023). "In the Biostat-HF and ASIAN-HF registries, women treated with ACE inhibitors, ARBs, and beta-blockers had approximately 30% lower risk of death or hospitalization for heart failure at 50% of the guideline recommended doses." (PMID 36937911, 2023). "Although pharmacological advances including beta blockers and angiotensin-converting enzyme (ACE) inhibitors reduce mortality, the residual risk of post-MI heart failure remains high." (PMID 35271504, 2022). "For instance, 11.8% (n = 76) of all ADEs with a causal relationship were related to the trigger ‘heart failure’, with the majority of these ADEs being adjudicated as underuse of beta-blockers, ACE-inhibitors, and diuretics." (PMID 35635713, 2022). "ACE inhibitors and angiotensin II receptor blockers (ARBs) are also known to reduce the risk of hospitalization for heart failure in an ethnicity-dependent manner." (PMID 34947975, 2021). "While several patient characteristics and conditions are associated with reduced soluble ACE levels, worsening of comorbidities such as heart failure or diabetes leads to rising soluble ACE2 levels." (PMID 35498160, 2021). "In general, the beneficial effects of ACE inhibitors in heart failure were associated with antihypertrophic effects and attenuation of ventricle enlargement in a number of both experimental and clinical studies." (PMID 34566652, 2021). "The mainstay of current medical management of DMD associated cardiomyopathy is the use of generic heart failure medications, including ACE inhibitors and beta blocker therapy." (PMID 34130633, 2021). "A previous study showed that ELA prevented pressure overload-induced heart failure, possibly via the suppression of angiotensinogen (ACE) expression and pathogenic angiotensin II signaling, in mice." (PMID 33282918, 2020).
heart failure (continued). "The PARADIGM‐HF trial showed that treatment with LCZ696 in heart failure patients significantly reduced the rate of deaths and hospitalization from cardiovascular causes compared to ACE inhibitor." (PMID 32026607, 2020). "Cardiac failure caused by AL amyloidosis can be treated with diuretics but ACE inhibitors and angiotensin II inhibitors are poorly tolerated by patients with cardiac amyloidosis, and the use of such agents can cause profound hypotension." (PMID 30808934, 2019). "Alternatively, it is possible that ACE inhibitors are more effective than aldosterone blockers at ameliorating heart failure risk in this population." (PMID 28716801, 2017). "Because of borderline estimates, ACE inhibitors were potentially associated with a decreased risk of heart failure hospitalization compared with placebo: 0.86 (95% CrI 0.73–1.01; moderate confidence)." (PMID 26954482, 2016). "Recently, clinical data are promising for chronic heart failure patients with reduced ejection fraction as they are superior to angiotensin-converting enzyme (ACE) inhibition by reducing risk of death and hospitalization in heart failure." (PMID 25622251, 2015). "In patients with AF and heart failure, the use of beta-blockers and ACE was associated with a 42% reduction in mortality." (PMID 28392870, 2014). "Some researchers suggest a high risk of heart failure results in less frequent use of β-blockers and more frequent prescription of ACE inhibitors." (PMID 20964853, 2010). "-In the case of uncontrolled HT, we have administered last resort ACE inhibitors, aswe preferred the increase of N retention, and the diminishing of diuresis, thisleading to a lower risk of stroke or aggravation of cardiac insufficiency." (PMID 20968199, 2010). "Appropriate treatment for heart failure is essential and is similar to that of other causes which include diuretics, β-blockers and ACE inhibitors." (PMID 20062635, 2009). "ACE inhibitors can cause acute renal failure in patients who are hypovolemic or who have severe heart failure, severe bilateral renal artery stenosis, or severe stenosis in the artery to a solitary kidney." (PMID 18947424, 2008). "The management of AKI from ACE inhibitors involves prompt recognition, discontinuation of the offending drug, and a close follow-up for patients with a higher risk such as those with chronic kidney disease, heart failure, or volume depletion." (PMID 40137155, 2025). "Early reperfusion therapy and some of the drugs that reduce the risk of mortality and heart failure following MI prevent progressive adverse remodelling (e.g. angiotensin‐converting enzyme [ACE] inhibitors, angiotensin receptor blockers [ARB], and beta‐blockers)." (PMID 39675781, 2025). "Screening for heart failure and its precursor, left ventricular dysfunction, could allow patients to receive therapies shown to reduce the risk of incident heart failure, such as ACE inhibitors and beta blockers." (PMID 40205856, 2025). "This divergence includes higher mortality rates among women taking digoxin for heart failure, increased risk of torsade de pointes arrhythmia with QT-prolonging drugs, and a higher incidence of cough associated with angiotensin-converting enzyme (ACE) inhibitors." (PMID 38975366, 2024). "ACE inhibitors can be used as first-line treatment for patients with IS, as they can prevent recurrent stroke and reduce the risk of other CVDs such as stable ischemic heart disease, AF, and heart failure." (PMID 39057558, 2024). "Despite the heterogeneity, anti-hypertensive thiazide diuretics, along with angiotensin-converting enzyme (ACE) inhibitors and angiotensin receptor blockers, remain one of the most commonly used medications for heart failure, especially in patients with elevated risk factors." (PMID 38915742, 2024).
heart failure (continued). "Given the sharp deterioration in the quality of life associated with heart failure, healthcare interventions should focus considerably more on this endpoint, especially those that use medications such as ACE inhibitors and beta-blockers, which have been demonstrated to enhance the quality of life." (PMID 38090453, 2023). "In a prior meta-analysis, the use of angiotensin-converting enzyme inhibitors (ACE-Is) and angiotensin receptor blockers (ARBs) reduced the relative risk of AF by 28% (p=.00002) with significant reductions seen in heart failure and left ventricular hypertrophy." (PMID 36999694, 2023). "In the work presented here we explored the proteome and phosphoproteome changes associated with a model of heart failure, and define for the first time global changes resulting from treatment with β-AR blocker (metoprolol) and ACE inhibitor (enalapril) in HFrEF hearts as well as in control hearts." (PMID 35306519, 2022). "In patients with heart failure with a reduced left ventricular ejection fraction (HFrEF), sacubitril/valsartan has been demonstrated to be superior to ACE inhibitors (ACEi) in decreasing the risk of heart failure hospitalization and death, and in reversing left ventricular remodeling." (PMID 35806967, 2022). "Publication of data from the Randomized Aldactone Evaluation Study showed that spironolactone reduced mortality by 30% compared with the mortality rate associated with placebo in patients with severe heart failure already receiving angiotensin-converting enzyme (ACE) inhibitors." (PMID 33214722, 2021). "ACE insertion/deletion (ACE I/D) genotype was suggested to be a genetic trait locus determining circulating ACE levels and was associated with various cardiovascular diseases, including heart failure." (PMID 34359878, 2021). "Since using neprilysin inhibitor alone will increase angiotensin II level, therefore, combining sacubitril with either ACE inhibitors or renin inhibitors could provide further relief of neurohumoral changes associated with heart failure." (PMID 31053170, 2019). "In addition, an absolute LVEF decline of > 10% can suggest an increased risk of heart failure and treatment with an ACE inhibitor is advised." (PMID 32154011, 2019). "This might be of potential concern as the previous explanations for similar findings on the hazardous effects associated with ACE inhibitors on survival, such as confounding by heart failure and use of old data, were addressed by this study." (PMID 28119386, 2017). "As shown, patients with RVDYS were similar with respect to CAD risk factors, but were more likely to require heart failure medications such as ACE inhibitors or loop diuretics, consistent with larger MI size and higher pulmonary artery (PA) pressure (all p<0.05)." (PMID 28961271, 2017). "Given the fact that ACE inhibitors are the cornerstone medical therapy for heart failure, this effect may be relevant in the observed association with heart failure incidence." (PMID 27052923, 2016). "With placebo as reference treatment, ARB alone or in combination with ACE inhibitor seemed to be associated with a reduced risk of hospitalization for heart failure: 0.86 (95% CrI 0.72–0.99; moderate confidence) for ARB and 0.75 (95% CrI 0.60–0.91; moderate confidence) for ACE inhibitor plus ARB." (PMID 26954482, 2016). "Hydralazine plus isosorbide dinitrate should be added to African-American patients with New York Heart Association class III or IV heart failure with a reduced left ventricular ejection fraction (HFrEF) already receiving diuretics, beta blockers, and an ACE inhibitor or ARB." (PMID 26718096, 2015). "However, the ability of ACE inhibitors or ARBs to prevent cardiac failure associated with AF, when used in its diagnostic, has yet to be evaluated." (PMID 28392870, 2014).